CCN2 (cellular communication network factor 2)
Description:
Major connective tissue mitoattractant secreted by vascular endothelial cells. Promotes proliferation and differentiation of chondrocytes. Is involved in the stimulation of osteoblast differentiation and has a critical role in osteogenesis. Mediates heparin- and divalent cation-dependent cell adhesion in many cell types including fibroblasts, myofibroblasts, endothelial and epithelial cells. Enhances fibroblast growth factor-induced DNA synthesis.
Synonyms: IBP-8; CTGF; HCS24; IGFBP8; KMD; NOV2; SEMDLSL
Tractability: Antibody: a drug acting on it is in phase 2 or 3 trials; UniProt places it where antibodies can reach, with high confidence; its Gene Ontology location is reachable by antibodies, with high confidence; UniProt predicts a signal peptide or a membrane-spanning region. PROTAC: ubiquitination databases record sites on it.
Target class: Adhesion
Gene: Protein-coding gene on chromosome 6 (131,948,176 to 131,951,456, reverse strand). Ensembl gene ENSG00000118523.
Subcellular location: Secreted, extracellular space, extracellular matrix; Secreted
Subcellular location (Human Protein Atlas): Golgi apparatus; Vesicles; Predicted to be secreted
Pathways (Reactome):
Gene expression (Transcription): RUNX3 regulates YAP1-mediated transcription; YAP1- and WWTR1 (TAZ)-stimulated gene expression
Gene Ontology:
Molecular function: protein binding; heparin binding; insulin-like growth factor binding; integrin binding
Biological process: osteoblast differentiation; positive regulation of cell differentiation; positive regulation of ERK1 and ERK2 cascade; positive regulation of JNK cascade; positive regulation of stress fiber assembly; cell adhesion; epidermis development; response to wounding; signal transduction; regulation of developmental process
Cellular component: extracellular matrix; extracellular region; non-collagenous component of interstitial matrix; plasma membrane
Genetic constraint (gnomAD): Loss-of-function variants: 22 observed, 29.93 expected, observed/expected ratio (o/e) 0.74, 90% interval 0.52 to 1.05. The upper end of that interval is the gene's LOEUF score, 1.05, which puts it in group 4 of 6, group 1 being the genes least tolerant of losing a copy. Missense variants: 469 observed, 455.66 expected, observed/expected ratio (o/e) 1.03, 90% interval 0.95 to 1.11. Synonymous variants: 178 observed, 180.05 expected, observed/expected ratio (o/e) 0.99, 90% interval 0.87 to 1.12.
Homologues: Orthologues: chimpanzee CCN2 (99% identical), macaque CCN2 (97% identical), pig CCN2 (93% identical), rat Ccn2 (91% identical), mouse Ccn2 (91% identical), rabbit CCN2 (89% identical), guinea pig CCN2 (85% identical), tropical clawed frog ccn2 (79% identical), zebrafish ccn2a (77% identical). Paralogues in human: CCN3 (50% identical), CCN1 (48% identical), CCN4 (42% identical), CCN6 (39% identical), CCN5 (32% identical).
Diseases named in the same sentence as CCN2 in open-access papers:
CCN2 is named in the same sentence as 500 diseases in open-access papers, as found by Europe PMC text mining. Sharing a sentence is not in itself a finding about the gene and the disease. The quoted sentences say what the papers report.
liver fibrosis (231 papers, 2005 to 2026). "This hepatocyte-specific loss of Ccn2/Ctgf affected liver fibrosis since there were significant decreases of Slit2, aSMA and Collagen type I genes at mRNA levels." (PMID 36469291, 2023). "Whereas CCN2 has been strongly implicated in alcohol-, viral-, or toxin-mediated hepatic fibrosis in human or animal models, data are much less clear-cut in the context of NASH fibrosis." (PMID 37629004, 2023). "In the liver, CCN2 expression is associated with hepatic fibrosis in both human subjects and animal models." (PMID 16303051, 2005). "Some SNPs in CCN2 have been associated with an increased risk of developing several human pathologies, mainly related to fibrotic disorders, including systemic sclerosis, pulmonary fibrosis, colon carcinoma, diabetic nephropathy and hepatic fibrosis." (PMID 36499730, 2022). "Furthermore, studies in various animal models have demonstrated that targeting genes encoding CTGF/CCN2 proteins in liver fibrosis may be therapeutically beneficial." (PMID 22978413, 2012). "miR-214, a versatile miRNA in various biological processes and fibrosis, attenuates liver fibrosis by targeting connective tissue growth factor (CCN2)." (PMID 40242037, 2025). "Consistently, elevated serum ALT level reduced significantly after HepG2 EV treatment, which also caused a dramatic attenuation of ACTA2 protein production and reduced expression of liver fibrosis-associated genes including COL1A1 and CCN2." (PMID 40002688, 2025). "Quiescent HSCs release EVs containing miR-199a-5p, which can be absorbed by aHSCs and suppress their CCN2 expression level by binding with the 3’-UTR (untranslated region) of CCN2 to reduce liver fibrosis." (PMID 39396032, 2024). "For example, our analysis of human NASH gene datasets showed that hepatic CCN2 mRNA expression is positively correlated with the hepatic fibrosis stage, consistent with several earlier studies of CCN2 protein as assessed by IHC." (PMID 37629004, 2023). "We found that Ccn2/Ctgf was highly upregulated in periportal hepatocytes during carbon tetrachloride-induced hepatocyte damage, liver fibrosis and cirrhosis in mice and rats." (PMID 36469291, 2023). "Collectively, these observations indicated that Ccn2/Ctgf formed complexes with Slit2 and its ectopic expression promoted liver fibrosis." (PMID 36469291, 2023). "A study showed that exosome-derived MiR-214 targets CCN2 directly regulates the expression of CCN2, and inhibits the process of liver fibrosis." (PMID 37461343, 2023). "As a potentially important pro-fibrotic molecule in hepatic fibrosis, CCN2 is upregulated by oxidative stress in various diseases." (PMID 35038159, 2022). "Exosomes derived from HSCs carrying connective tissue growth factor (CCN2) participate in the induction of liver fibrosis." (PMID 33247543, 2021). "Therefore, CCN2 in serum exosomes is considered to play an important role in the pathological process of liver fibrosis and may function as a marker for assessing the risk of liver fibrosis to progress to HCC." (PMID 31815633, 2019). "LIG prevents and alleviates the development of liver fibrosis by downregulating TGFβ1, TβRII, CCN2, and Smad2/3, and type I collagen while upregulating Smad7 and inhibits proliferation of hepatic stellate cells." (PMID 31886227, 2019). "Collectively, these results suggested that Activin A exerted its fibrotic role through the induction of CTGF/CCN2 in LPCs, and our results provided new evidence in the relationship between LPCs and liver fibrosis." (PMID 27011166, 2016). "Several secreted or intracellular factors related to cell regulation (“signaling pathway”) were also upregulated, some of them (Trib3, CTGF/CCN2, Egr1, Stat3...) having been linked to inflammation, tissue repair, liver fibrosis and TGFβ signaling." (PMID 26446156, 2016). "Previous studies demonstrated that in addition to promoting liver fibrosis, CTGF/CCN2 was critical for the expansion of LPCs during LPC-mediated liver regeneration." (PMID 27011166, 2016).
liver fibrosis (continued). "It is over-expressed in many fibrotic disorders including scleroderma, kidney and liver fibrosis and constitutive expression of CCN2/CTGF in tissues is considered to indicative for pathological lesions." (PMID 21209863, 2010). "Furthermore, in hepatocytes, TGF-β and activin A signaling are key players in liver fibrosis by inducing autonomous synthesis of connective tissue growth factor (CTGF/CCN2)." (PMID 40304568, 2025). "Moreover, inhibition of CCN2 attenuated liver fibrogenesis in a carbon tetrachloride-induced liver fibrosis mouse model." (PMID 35038159, 2022). "Recent evidence has demonstrated that LPCs may contribute to liver fibrosis through the release of factors including connective tissue growth factor (CTGF/CCN2) that induce the production of an excessive extracellular matrix (ECM)." (PMID 27011166, 2016). "Our investigation provides molecular evidence for the fibrotic role of LPCs in the liver and suggests that the Activin A-Smad-CTGF/CCN2 axis in LPCs may be a potential therapeutic target of liver fibrosis." (PMID 27011166, 2016). "Previous studies have reported that the expression of Activin A is elevated in the fibrotic liver and Activin A contributes to liver fibrosis through induction of fibrotic matricellular proteins such as CTGF/CCN2 in hepatocytes and hepatic stellate cells (HStCs)." (PMID 27011166, 2016). "Collectively, these results provide evidence for the fibrotic role of LPCs in the liver and suggest that the Activin A-Smad-CTGF/CCN2 signaling in LPCs may be a therapeutic target of liver fibrosis." (PMID 27011166, 2016). "Also, a humanized monoclonal antibody (FG-3019) directed at CCN2 has undergone safety trials in patients with diabetes mellitus and microalbuminuria, and is currently being tested in patients with idiopathic pulmonary fibrosis and liver fibrosis." (PMID 25384022, 2014). "PA-treated liver cells release EVs that induce upregulation of CCN2 expression in HSCs, which potentiates HSC activation and aggravates liver fibrosis." (PMID 40129979, 2025). "SIM inhibits the synthesis of growth factors including connective tissue growth factor (CTGF/CCN2) and TGFβ1, and reduces liver fibrosis." (PMID 36831004, 2023). "This study aimed to investigate functions of cellular communication network factor 2 (CCN2)/Connective tissue growth factor (CTGF), an extracellular signaling modulator of the CYR61/CTGF/Nov (CCN) family, in liver fibrosis." (PMID 36469291, 2023). "If CD8, CD14, and connective tissue growth factor (CCN2) are highly expressed in EVs, they can be used to assess the degree of liver fibrosis." (PMID 35692794, 2022). "As a result, it inhibits synthesis of growth factors including connective tissue growth factor (CTGF/CCN2) and TGFβ1, and reduces liver fibrosis." (PMID 33925827, 2021). "Our previous investigation reported that LPCs produced connective tissue growth factor (CTGF/CCN2), an inducer of liver fibrosis, yet the regulatory mechanism of the production of CTGF/CCN2 in LPCs remains elusive." (PMID 27011166, 2016). "CTGF/CCN2 is one of the most important fibrotic matricellular proteins and serves as a master switch in liver fibrosis." (PMID 27011166, 2016). "Echinacoside, a natural phenol belonging to the phenylpropanoid class of caffeic acid glycosides, suppresses liver fibrosis in vivo by reducing the expression of TGF-β1, β-catenin, Smad4, MMP-9, PI3K, mTOR, cellular communication network factor 2 (CCN2), platelet-derived growth factor-B (PDGFB)." (PMID 40655154, 2025). "The down-regulation of CCN2 expression inhibits ECM secretion, slowing liver fibrosis progression." (PMID 40242037, 2025). "In patients with MASH exhibiting F3-F4 fibrosis, activated HSCs and myofibroblasts exhibited a marked upregulation of the pro-fibrotic molecule, Cell Communication Network Factor 2 (CCN2), which subsequently potentiated HSC activation and aggravated liver fibrosis." (PMID 40129979, 2025).
liver fibrosis (continued). "CCN1, CCN2, and CCN3 have each been studied to some degree in liver fibrosis." (PMID 35038159, 2022). "Additionally, HSCs and hepatocytes produce “connective tissue growth factor (CTGF, also known as CCN2)”, which is highly expressed during liver fibrosis." (PMID 34965258, 2021). "Interestingly, in renal, vascular, and hepatic fibrosis models, Ang-II can induce Smad-dependent signaling through the AT1 receptor in a TGF-β-independent manner, increasing CCN2/CTGF levels." (PMID 34063397, 2021). "Several studies showed that the other CCN family member, connective tissue growth factor (CTGF/CCN2), facilitates liver fibrosis in humans and animal models, whereas CYR61/CCN1, in contrast, promotes regression of liver fibrosis through induction of cellular senescence in hepatic myofibroblasts." (PMID 33946738, 2021). "While there was no improvement of NASH fibrosis in the FLIRT study, hepatic fibrosis was, nonetheless, improved by rosiglitazone in MCD diet-fed C57BL6/J mice, and this was attributed to activation of PPARγ, which caused reduced HSC activation and suppressed expression of TGF-β1 and CCN2." (PMID 37629004, 2023). "Since expression of CCN2 and integrins is enhanced during HSC activation and liver fibrosis, persistence of the activated fibrogenic phenotype in HSC may occur, at least in part, by NF-κB survival pathways that are triggered via the binding of CCN2 to its integrin αvβ3 receptor." (PMID 16303051, 2005). "Furthermore, HSC-derived sEVs contained connective tissue growth factor (CCN2), and its concentration increased with HSC activation, which may amplify or fine-tune fibrotic signal transduction and may be considered as a potential candidate biomarker to assess hepatic fibrosis." (PMID 37180779, 2023).
pulmonary fibrosis (201 papers, 2007 to 2025). Chronic progressive interstitial lung disorder characterized by the replacement of the lung tissue by connective tissue, leading to progressive dyspnea, respiratory failure, or right heart failure. "In this study we focused on the role of CCN2 in lung fibrosis as pulmonary involvement is the leading cause of death in SSc." (PMID 33662577, 2021). "CCN1, a member of the CCN family of matricellular proteins, has similar in vitro functions to CCN2 and is associated with lung fibrosis." (PMID 29049376, 2017). "Secreted factors such as transforming growth factor β1 (TGFB1) and connective tissue growth factor (CTGF, also known as CCN2) are the notorious pro-fibrotic agents involved in the initiation and progression of pulmonary fibrosis." (PMID 38900131, 2024). "From those only two had fibrotic indications, STX-100 targeting ITGAV and Pamrevlumab targeting CCN2, both for pulmonary fibrosis indications." (PMID 36531712, 2022). "As a matter of fact, a neutralizing antibody against human CCN2 was developed and subjected to clinical trials for the treatment of idiopathic pulmonary fibrosis, muscular dystrophy, diabetes and locally advanced pancreatic cancer cases." (PMID 35682564, 2022). "A previous study indicated that CCN2 interacts with FN to induce lung fibrosis via the integrin signaling pathway." (PMID 36578010, 2022). "In this study, genetic manipulation of the CCN2 gene was employed to investigate the role of CCN2 expression in vitro and in experimentally-induced models of pulmonary fibrosis and pulmonary arterial hypertension (PAH)." (PMID 33662577, 2021). "The data from the present study show that fibroblast-specific CCN2 deletion protects against bleomycin-induced lung fibrosis and pulmonary hypertension." (PMID 33662577, 2021). "To investigate the effect of fibroblast-specific CCN2 deletion on the development of lung fibrosis, we examined the extent of bleomycin-induced pulmonary remodeling, in tamoxifen-induced CCN2 KO mice." (PMID 33662577, 2021). "We also found that fibroblast-specific CCN2 knockout mice showed significant resistance to bleomycin-induced pulmonary fibrosis and pulmonary hypertension." (PMID 33662577, 2021). "An anti-CCN2 antibody (FG-3019) is in Phase III clinical trials for idiopathic pulmonary fibrosis and pancreatic cancer, and in Phase II for Duschenne's muscular dystrophy." (PMID 32410169, 2020). "Adding to this, mice heterozygous for TAZ show a remarkable resilience against bleomycin-induced pulmonary fibrosis, possibly due to reduced levels of CCN2 (CTGF), one of the YAP and TAZ target genes." (PMID 26389119, 2015). "A CCN2 response element exists in the COL1A2 promoter, and recently it has been shown that blocking CCN2 action using an anti-CCN2 antibody or small interfering RNA reduces aspects of bleomycin-induced lung fibrosis." (PMID 23690667, 2013). "CTGF (CCN2) is regarded as one of the key fibrogenic cytokines in the development of pulmonary fibrosis." (PMID 24351828, 2013). "A CCN2 response element exists in the COL1A2 promoter; blocking CCN2 action using an anti-CCN2 antibody or siRNA reduces some effects of bleomycin-induced lung fibrosis." (PMID 20507556, 2010). "A human monoclonal anti-CCN2 antibody, known as FG-3019 or Pamrevlumab, has been developed and is in phase 3 clinical trials for use in treating multiple diseases, including Duchene muscular dystrophy and idiopathic pulmonary fibrosis." (PMID 37762168, 2023). "Indeed clinical trials with therapeutic anti-CCN2 antibodies in patients with idiopathic pulmonary fibrosis are currently ongoing." (PMID 37245184, 2023). "Indeed, an anti-CCN2 antibody was shown to be effective to slow down the progression of idiopathic pulmonary fibrosis." (PMID 35682564, 2022). "Taken together, CCN2 plays a role in mediating lung fibrosis." (PMID 36578010, 2022). "A previous study showed that inhibition of CCN2 could attenuate lung fibrosis in bleomycin-treated mice." (PMID 36578010, 2022).
pulmonary fibrosis (continued). "The work from this study provides support for blockade of CCN2 expression or activity as a feasible therapeutic option for pulmonary fibrosis and pulmonary hypertension such as that in SSc and other diseases where CCN2 is overexpressed and plays a key role in pathogenesis." (PMID 33662577, 2021). "CCN2/CTGF is highly overexpressed in conditions associated with increased extracellular matrix (ECM) synthesis and fibrosis such as scleroderma, diabetic nephropathy and kidney fibrosis, fibrotic liver diseases, idiopathic pulmonary fibrosis, or glaucoma." (PMID 33512643, 2021). "Connective tissue growth factor (CTGF) or cellular communication network factor 2 (CCN2) is a fibrosis-related gene upregulated in many diseases such as idiopathic pulmonary fibrosis, Duchenne muscular dystrophy, and cancers, including unresectable pancreatic cancer." (PMID 33050151, 2020). "Therefore, targeting CCN2 using an anti-CCN2 antibody approach may also be a feasible option for the treatment of lung fibrosis in SSc patients." (PMID 33662577, 2021). "Connective tissue growth factor (CTGF, CCN2), a cysteine-rich matricellular protein, is an important profibrotic mediator in several fibrotic disorders, including idiopathic pulmonary fibrosis (IPF)." (PMID 34122421, 2021). "Apart from phenotypic alterations, AECs also produce various pro‐fibrotic cytokines/growth factors such as TGF‐β1 and connective tissue growth factor (CTGF/CCN2), which further trigger EMT, and to aggravate lung fibrosis." (PMID 32705806, 2020). "The present results indicate that persistent tenascin-C deposition contributes to the pathological persistence of skin and lung fibrosis, and is along with TGF-β, CCN2 and others, a major factor in the process." (PMID 27256716, 2016). "Together these findings indicated that atorvastatin protects rats against bleomycin-induced pulmonary fibrosis, at least in part, by the inhibiting the CTGF (CCN2)/ERK signaling pathway." (PMID 24351828, 2013). "Taken together, atorvastatin significantly ameliorated bleomycin-induced pulmonary fibrosis in rats, via the inhibition of iNOS expression and the CTGF (CCN2)/ERK signaling pathway." (PMID 24351828, 2013). "In addition, anti-CCN2 therapy is in phase 2 or 3 clinical trials in other diseases, including Duchenne muscular dystrophy (NCT02606136), idiopathic pulmonary fibrosis (NCT03955146), and pancreatic adenocarcinoma (NCT04229004)." (PMID 35204752, 2022). "Furthermore, there are clinical trials in phase 2 or 3 using anti-CCN2 therapies in Duchenne muscular dystrophy (NCT02606136), pancreatic adenocarcinoma (NCT04229004) and idiopathic pulmonary fibrosis (NCT03955146)." (PMID 36499730, 2022). "Our findings suggest that atorvastatin may down-regulate CTGF (CCN2) protein expression, thus, modulating the collagen synthesis in bleomycin-induced pulmonary fibrosis." (PMID 24351828, 2013).